STAT3 (signal transducer and activator of transcription 3)
Diseases named in the same sentence as STAT3 in open-access papers (continued):
Sharing a sentence is not in itself a finding about the gene and the disease.
cancer (continued). "Specifically, it has been reported that when PARP1 is aberrantly activated in cancer cells, it blocks phosphorylation of STAT1 and STAT3 via the poly(ADP-ribosyl)ation, ultimately reducing their transcriptional activity." (PMID 37190289, 2023). "The roles of STAT3 and STAT1 in this system agree well with the potential use of STAT proteins as targets in cancer therapy, as has been suggested and addressed in different studies and in clinical trials." (PMID 37830552, 2023). "The control group presented higher expression levels of SCFA and FFAR2, while the cancer group had higher levels of TNFAIP8, IL6, and STAT3." (PMID 37893122, 2023). "Hsp90 is often overexpressed and associated with poor prognosis in a variety of tumors because it promotes the activation of oncogenic protein kinases, e.g., JAK2/STAT3, PI3K/AKT, and MAPK, facilitating cancer progression." (PMID 37190332, 2023). "In conclusion overexpression of STAT3 can promote the development and growth of tumors by regulating IME, which is significantly related to the poor prognosis of cancer patients." (PMID 37724127, 2023). "The CCL5/CCR5 axis contributes to cancer cell proliferation, metastasis, and the formation of an immunosuppressive microenvironment via the PI3K/Akt or STAT3 signaling pathway." (PMID 37553567, 2023). "It is known to accelerate cancer progression by activating the PI3K, MAPK, and STAT3 signaling pathways." (PMID 37954072, 2023). "STAT proteins, particularly STAT1, STAT3, STAT5A and STAT5A, have been found to be hyperactivated in many cancers." (PMID 38255152, 2023). "Some pathways showed dual roles such as Kras signaling, interferon gram and alpha response, IL6/JAK/STAT3, IL2/STAT5 signaling were negatively enriched in HOXC10 for CESC, COAD, ESCA, HNSC but were positively enriched in HOXC10 for other cancers." (PMID 38154103, 2023). "In conclusion, we found that UA alleviates cancer cachexia and prevents muscle wasting via activating SIRT1, and thence inhibiting phosphorylation levels of NF-κB and STAT3." (PMID 37190306, 2023). "CD24 enhances the upregulation of STAT3-dependent genes, such as cyclin D1, survival protein, and MCL-1, thus promoting survival and proliferation of cancer cells." (PMID 38137380, 2023). "Immunoblot analysis of protein expression level in tumors showed that tumors induced by cancer cells stably expressing STK24+shnc had higher STAT3 and VEGFA expression levels as compared with to tumors induced by cancer cells stably expressing vector+shnc." (PMID 36720310, 2023). "Quercetin, in turn, stops cancer cells in the G0/G1 phase of the cell cycle, promotes apoptosis, and reduces angiogenesis by interfering with the PI3K/AKT/mTOR and STAT3 pathways." (PMID 37570691, 2023). "The results showed that HDAC3 silencing reduced the phosphorylation of CDK1 Y15 and STAT3 Y705 followed by reduction of CD44 and Sox2, which resulted in the impairment of cancer cell stemness." (PMID 37743465, 2023). "For instance, TAMs increase cancer cell invasion and capability for metastasis through induction of EMT by interfering with JAK2/STAT3/miR-506-3p/FoxQ1 regulation of colorectal cancer development." (PMID 38033495, 2023). "Recently, several studies reported STAT3 and its activation as another important target of FLU in cancer cells." (PMID 37045903, 2023). "Studies have identified a key oncogenic role for STAT3 in NSCLC: participating in the promotion of many cancer hallmarks, such as immune suppression, cell survival, angiogenesis, drug resistance, and cancer cell stemness." (PMID 36672335, 2023). "In cancer cells, NFZ has been reported as a potent inhibitor of the signal transducer and activator of transcription 3 (STAT3)." (PMID 37409934, 2023). "It was identified as a growth factor for hepatocytes and some other cancer cells and activates the signaling via the ERK 1/2 and STAT3 pathways." (PMID 36982417, 2023).
cancer (continued). "The relative amino-acid change enhances the recruitment and activation of signal transducer and activator of transcription 3 (STAT3), and, thus, accelerates cancer progression." (PMID 36983691, 2023). "Upon IL-22 and IL-6 stimulation in epithelial cells, the activation of the STAT3 pathway not only enhances cell viability but also suppresses suppressing apoptosis, underscoring its significance in the transition from IBD to cancer." (PMID 38288125, 2023). "In fact, it has been found that STAT3 (and other STAT family members, including STAT5) is activated commonly in a wide spectrum of human cancers." (PMID 38022653, 2023). "HIF-1 and STAT3 are recognized as key inducers of VEGF expression and are upregulated in multiple cancer types." (PMID 37047688, 2023). "Besides, inhibition of Hsp110-STAT3 interaction with the small molecule could effectively suppress cancer cell growth by decreasing phosphorylated STAT3 and c-Myc protein levels.Nonetheless, it remains unclear whether Hsp110-STAT3 interaction plays an important role in pulmonary vascular remodeling." (PMID 37978368, 2023). "To investigate this, we probed the interaction between STAT3 and JAK2 in cancer cells expressing either Vector or PRMT6." (PMID 37813837, 2023). "This modification proved indispensable for STAT3’s membrane localization, its interaction with JAK2, STAT3 Y705 phosphorylation, and PRMT6-driven cancer cell metastasis." (PMID 37813837, 2023). "Anther study found STAT3 signaling, mediated by TFF1 silencing, promotes gastric inflammation-cancer transformation." (PMID 37964307, 2023). "Studies in EC and GC have also demonstrated the cancer promoting properties of CAF-secreted IL-6, which promotes EMT and metastasis via JAK2/STAT3 signaling pathway." (PMID 38455361, 2023). "Significantly, Embelin also modulates critical signaling pathways involved in cancer pathophysiology, such as NF-κB, PI3K/Akt, and interleukin-6/STAT3 signaling pathways." (PMID 38234968, 2023). "The persistent activation of STAT3, a downstream target of HSP90, is known to promote cell proliferation and survival in cancer, making it a promising target for cancer therapy." (PMID 38002524, 2023). "The STAT3 inhibitor TTI-101 (Tvardi Therapeutics, Incorporated, USA) is now undergoing testing in a phase I clinical trial in patients with advanced cancers (clinicaltrials.gov ID NCT03195699)." (PMID 37308559, 2023). "SOCS1/3 are negative regulators of the IL-6/STAT3/NFKB axis, whose dysfunction leads to various cancers." (PMID 38023123, 2023). "This was followed by mTOR/STAT3 pathway inactivation, which ultimately inhibits proliferation and induces caspase-dependent apoptosis in ovarian SKOV-3/CDDP cancer cells." (PMID 37446140, 2023). "Activation of the JAK/STAT3 signaling pathway also increases tumorigenesis and metastasis via enhanced EMT and CSC transition, leading to cancer chemoresistance." (PMID 37394580, 2023). "It was verified that the upregulation of HIF-1α, STAT3, and VEGF in tumor cells was likely to enhance the microvessel density and promote the progression of some cancers." (PMID 37333486, 2023). "From the network pharmacology analysis, it was found that the main targets for inhibiting BPH are AKT1, TNF, EGFR, STAT3 and PTGS2, which are enriched in pathways in cancer." (PMID 37446563, 2023). "It is well known that STAT3 contributes to the development of HCC by promoting growth, anti-apoptosis, migration, invasion, angiogenesis, cancer stem cell characteristics, and immune suppression of cancer cells." (PMID 38322013, 2023). "Stattic, a small molecular inhibitor of STAT3, was used to block the phosphorylation of STAT3 in HCT116 cancer cells." (PMID 38001065, 2023). "Study showed that down-regulation of phosphorylation of JAK2/STAT3 significantly inhibited its downstream target genes MMP-2/9, thereby suppressing cancer metastasis and invasion in NSCLC." (PMID 37766868, 2023).
cancer (continued). "Many investigators have shown that STAT3 inhibition can reverse ADR, restore the efficacy of anticancer agents, enhance anti-cancer immune responses, and rescue the suppressed immunologic system." (PMID 36902166, 2023). "STAT3 and STAT5 activity is frequently elevated aggressive subtypes of cancer, making them valuable prognostic indicators." (PMID 37474926, 2023). "Tanshinone IIA can sensitize cancer cells to TRAIL-induced apoptosis by upregulating DR5 or selectively activating PERK/ATF4 and inhibiting STAT3." (PMID 37990309, 2023). "For instance, the activated STAT3 enriches the expression of CD44, physically interacts with CD44 and NF-κB, activates the telomerase (hTERT), promotes a cancer stem phenotype." (PMID 37642779, 2023). "In conclusion, UEC and OCC showed high HIF-1α, STAT3, and PSMA expression, indicating that both cancer types share developmental and progression pathways." (PMID 37713813, 2023). "Scopolamine D suppresses p-STAT3 expression in CNE-2 cells, and this suppression can aid in triggering apoptosis and restraining migration in cancer cells." (PMID 38202691, 2023). "As one of the most dysregulated signaling pathway in cancer, especially in breast cancer, many therapies targeting the IL6/JAK/STAT3 signaling pathway have been developed and studied." (PMID 37173331, 2023). "It is widely accepted that IL-17 promotes cancer development and progression by modulating oncogenic kinase signaling pathways, including the MAPK, PI3K/Akt, and JAK/STAT3 pathways." (PMID 37894738, 2023). "Dual inhibition of STAT3 and KRAS, achieved by nano-antibody SBT-100, would be an ideal treatment for this type of cancer to overcome ADR in ovarian and many other types of cancer." (PMID 36902166, 2023). "Various studies have reported that STAT3 induces crosstalk between the JAK/STAT pathway and other signaling pathways, such as MAPK/MEK/ERK and PI3K/Akt, promoting cancer progression, chemo-resistance development, and the epithelial–mesenchymal transition." (PMID 37512149, 2023). "IL-6 is secreted by various cell types in TME, including immune cells, stromal cells, and cancer cells, inducing the activation of Janus kinase (JAK)/STAT3 signaling, which in turn drives immunosuppression." (PMID 38313431, 2023). "Collectively, our findings illuminate the potential benefits of targeting PRMT6 as a therapeutic strategy to counteract both the STAT3 signaling pathway and the H3R2-mediated epigenetic mechanisms, offering new avenues for enhancing cancer treatment outcomes." (PMID 37813837, 2023). "TGF-β is involved in regulating the biological function of malignant tumors in several ways, including Jagged1/Notch, Wnt, JAK2/Stat3, and PI3K/AKT/mTOR." (PMID 37240338, 2023). "STAT3 activation was identified to be 10.6- and 8.8-fold higher in tumors and normal mucosa, respectively, of HNSCC patients compared to the mucosa of non-cancer patients, supporting the concept of “field cancerization”." (PMID 37511453, 2023). "The IL-6/STAT3 pathway is abnormally activated in HCC, which results in increased progression, invasion, and migration of the cancer cells." (PMID 37095578, 2023). "In five human cell lines, including cancers and EBV-transformed B lymphocytes, a significant enrichment of ERα binding was demonstrated within the STAT3 locus." (PMID 36899902, 2023). "Epithelial-mesenchymal transition (EMT) is a vital step in the early stages of cancer metastasis and orchestrated by multiple signaling pathways, such as IL-6/JAK/STAT3 and TGF-β/Smad signaling pathway." (PMID 37742009, 2023). "The individual silencing of STAT3, STAT1 on cancer cells was much prominent to suppress the MDR activity." (PMID 38304256, 2023). "Extensive studies have shown that STAT3, a protein related to STAT, is commonly activated in cancer." (PMID 36852795, 2023). "Collectively this observation suggests that MDSC augments early generation of drug resistance of cancer cells by IL-6/STAT1 and IL-10/STAT3 axis." (PMID 38304256, 2023).
cancer (continued). "In gastrointestinal cancer, STAT3 has been found to promote epithelial–mesenchymal transition (EMT), the initial step of cancer metastasis." (PMID 37375849, 2023). "ASX can play an anti-cancer role by blocking the transmission of PI3K/AKT, NF-κB and STAT3 signaling paths." (PMID 36969867, 2023). "STAT signaling is one of the most well-characterized mode of PD-L1 induction in cancer cells, but IL-1β primarily signals though NFκB pathway, therefore, we were surprised to see an increase in p-STAT1 and p-STAT3 levels in HCC827 cells treated with IL-1β." (PMID 37985999, 2023). "IL6 in turns activates STAT3 signaling pathway in CRC cells and increases the cancer cell invasiveness." (PMID 37062842, 2023). "Therefore, targeted inhibition of STAT3 expression or activity may have important research value for the development of combined immunotherapy and targeted therapy approaches for the treatment of cancer patients." (PMID 37724127, 2023). "Reports have illustrated that JAK2/STAT3 signaling upregulates cyclin D2 and stemness-related TFs to persistently maintain CSC stemness in cancers." (PMID 37853437, 2023). "Intriguingly, previous studies reported that STAT3 can be stimulated by the ER stress-dependent PERK and IRE1α pathways in glial and cancer cells." (PMID 36645345, 2023). "Our results demonstrated that, in cancer cachexia, a state of systemic inflammation contributes to the upregulation of the BMP scavenger ERFE through STAT3 activation." (PMID 38052214, 2023). "In this paper, we found that ursolic acid (UA) alleviated cancer cachexia and prevented muscle wasting via activating SIRT1, and thence inhibiting phosphorylation levels of NF-κB and STAT3." (PMID 37190306, 2023). "STAT1 and STAT3 are generally viewed as mediating opposite roles in cancer development, with STAT1 suppressing tumorigenesis and STAT3 promoting oncogenesis." (PMID 38022653, 2023). "This adipokine regulates glucose and lipid metabolism and can inhibit cell growth and induce apoptosis in cancer cells, mainly through activation of AMPK, MAPK, PI3K/AKT, or STAT3 signaling." (PMID 37481560, 2023). "Although STAT3 is demonstrated to be a transducer of other cytokines, CCR2 knockout study has shown to reduce PD-L1 expression in cancer cells." (PMID 37792212, 2023). "In particular, in NSCLC, MALAT1 is involved in STAT3, SRSF7, and PBOV1 (prostate and breast cancer overexpressed 1) pathways; MALAT1 affects the levels of miR-124, miR-374b-5p, and miR-28-5p, which in turn, target STAT3, SRSF7, and PBOV1 mRNAs, respectively." (PMID 35630580, 2022). "STAT3 is a member of STAT-family of transcription-factors and plays an important role in cancer related inflammation." (PMID 36557997, 2022). "Mechanistically, si-FLANC reduced STAT3-induced VEGFA expression, inhibiting OS and cancer progression." (PMID 35081965, 2022). "Andrographolide is known to inhibit the actions of STAT3, JAK1, and JAK2 phosphorylation in human cancer cells." (PMID 35682652, 2022). "In an in vitro model, IL-6 family cytokine oncostatin-M (OSM) induces cancer cell EMT and escape from the targeted drug-induced apoptosis in an OSM receptor (OSMR)/JAK1/STAT3-dependent manner." (PMID 35488263, 2022). "In addition, the importance of the SH2 structural domain in STAT3 has been increasingly recognized in recent years and a series of small molecule inhibitors has been designed to directly target STAT3, the functions of which have been demonstrated in preclinical studies of various cancers." (PMID 36291659, 2022). "EGCG strengthened the inhibitive effect of DOC on the PISK/Akt signaling pathway, the transduction and activation of STAT3, and the expression of MDR protein, leading to inhibition of cancer cell invasion and metastasis." (PMID 36545470, 2022). "In OSCC, the activation of the Jak/Stat3 signaling pathway has been shown to be able to promote the process of EMT and enhance the stemness of cancer cells." (PMID 34991668, 2022).
cancer (continued). "The correlative observations of low STAT3 activity and/or expression and high NKG2D ligands surface levels have also been made in other cancer entities." (PMID 35865518, 2022). "Studies have found that the STAT3/p-STAT3/GLUT1 pathway is involved in the metabolism and proliferation of cancer cells." (PMID 35359847, 2022). "B7-H4 overexpression activates a variety of signaling pathways, such as the NF-κB, ERK1/2, AKT/STAT3 and PI3K/AKT/mTOR pathways, to promote epithelial-mesenchymal transition (EMT) and invasion of cancer cells." (PMID 35410218, 2022). "Leptin has been suggested to strongly take part in cancer onset and proliferation, by activating several growth signaling pathways such as PI3K/Akt, MAPKs (ERK1/2), and JAK/STAT3, which drive cell-cycle progression acting on different target genes." (PMID 35681689, 2022). "SHP2 is known to inhibit Stat3 phosphorylation; high levels of SHP2 and low levels of p-Stat3 in tumors correlate with longer cancer patient survival." (PMID 36140747, 2022). "The uptake of such EVs by recipient breast cancer cell promotes cancer stemness and chemoresistance via enhanced EZH2/STAT3 signaling." (PMID 35646668, 2022). "The key driving forces behind cancer (CSC) stem cells, including PI3K/AKT/mTOR and JAK/STAT3, had been shown to be highly regulated in high-CSC cancers, and clinical trials are being conducted to identify small molecules that target these pathways." (PMID 35769912, 2022). "Among the novel PD-L1 enhancers, we demonstrated that WNK3, a less characterized protein in cancer, is necessary and sufficient for the transactivation of PD-L1 through its kinase activity in JNK-dependent but IFN-γ/STAT3-independent mechanisms." (PMID 36357569, 2022). "STAT3 is able to promote epithelial mesenchymal transformation in CRC, thus promoting cancer metastasis." (PMID 36046463, 2022). "Presently, an abundant amount of evidence has indicated that STAT3, as well as cytokine IL6 and IL8, potentially form a positive feedback loop in cancer patients while enhancing cisplatin resistance." (PMID 36292923, 2022). "A study found that administration of sunitinib, a tyrosine kinase inhibitor, to several types of cancer including CRC, reduced phosphorylated STAT3 and ARG levels in M-MDSC, and increased T-cell proliferation." (PMID 36081407, 2022). "IL-6 induces C-reactive protein production and affects cancer cell proliferation, invasion, metastasis, angiogenesis, and resistance to treatment via the JAK/STAT3 pathway." (PMID 36294421, 2022). "At the same time, previous studies have confirmed that the downstream genes of LNC00324 can induce cancer cells to develop resistance to chemotherapy, including IGF-1R, AKT1, and STAT3." (PMID 36620587, 2022). "STAT3 (respective STAT3α isoform) is involved in the EMT and self-renewal of cancer stem cells, promoting metastasis and invasion." (PMID 36429126, 2022). "Activation of the STAT3‐dependent pathways including the STAT3/FAK/ERK pathway, STAT3/Oct‐4 pathway in various cancer cells, and the IL‐8/STAT3 pathway and EGFR/STAT3/Sox‐2 pathways in TAMs are shown to contribute to the cancer stemness." (PMID 35356799, 2022). "Therefore, it is strongly proposed that n-3 PUFAs could be used as adjuvants for cancer treatments by targeting STAT3 and its downstream signaling proteins, which might be therapeutic targets with a good potential for HCC treatment due to its implication in cell growth and survival." (PMID 35566382, 2022). "STAT3 often works in concert with TGF beta and has been shown to be crucially involved in cancer cell dissemination." (PMID 35903898, 2022). "The expression level of OSMR correlates with the reactivity of OSM, and STAT3 activation induced by the OSM–OSMR interaction is observed in various cells, including cancer and immune cells." (PMID 36551576, 2022).